IL15 (interleukin 15)
Diseases named in the same sentence as IL15 in open-access papers (continued):
Sharing a sentence is not in itself a finding about the gene and the disease.
Sepsis (59 papers, 2011 to 2026). Sepsis is defined as life-threatening organ dysfunction caused by a dysregulated host response to infection. "IL-15-deficient (IL-15 KO) mice are resistant to septic shock but IL-15 treatment exacerbates the severity of sepsis by activating NK cells and promoting IFN-γ production." (PMID 38114466, 2023). "GEE results revealed that zone 1 ROP, stage 3 ROP, older baseline PMA, RDS, NEC, and sepsis were associated with increases or decreases in the serum levels of GM-CSF, IL-5, IL-15, ICAM-1, TNF-α, and TNFR-2 in premature infants." (PMID 38259597, 2023). "Members of the interleukin (IL)-2 receptor activating family of cytokines, such as IL-7 and IL-15, have been shown to improve survival in an experimental model of polymicrobial sepsis caused by cecal ligation and puncture (CLP)." (PMID 26859674, 2016). "The administration of IL-15 improved survival in two different models of sepsis and was associated with an increase in lymphocyte survival, decreased apoptosis of NK cells, dendritic cells, and T cells, and increased IFN-γ secretion." (PMID 25302303, 2014). "While, ω-3 PUFA supplementation protected against severe colitis, these mice suffered greater mortality associated with sepsis-related serum factors such as LPS binding protein, IL-15 and TNF-α." (PMID 23405155, 2013). "Elevated serum IL-15 levels in patients with sepsis after emergency abdominal surgery were associated with prognosis and organ dysfunction, with non-survivors having significantly higher basal IL-15 levels than survivors, and this difference persisted throughout the course of the study." (PMID 38114466, 2023). "Furthermore, IL-15 knockout mice, characterized by NK cell loss, also showed tolerance to sepsis due to CLP surgery." (PMID 36776839, 2023). "Importantly, MCMV is a pathogen within our infection regimen, and IFN-γ, IL-10, and IL-15 are produced during the sepsis-associated cytokine storm." (PMID 35878936, 2022). "Indeed, IL-15 treatment of infected mice was shown to prevent NK cell apoptosis, and in cases of polymicrobial sepsis and pneumonia, treatment was associated with improved survival." (PMID 23098236, 2012). "Another study has shown that subcutaneous injection of IL-15 can reduce T cell apoptosis in sepsis mice, increase the number and functional activity of NK cells and macrophages, and improve survival rates." (PMID 41209006, 2025). "The multivariate regression analysis showed that IL‐15 and IL‐18 contributed to the differentiation between sepsis and non‐sepsis patients." (PMID 40041474, 2025). "The administration of IL-15 exhibited a significant inhibitory effect on sepsis-induced apoptosis of CD8 T cells, natural killer cells, and dendritic cells." (PMID 38510969, 2024). "Immunomodulatory molecules such as IL-7, IL-15, and anti-programmed cell death 1 have been identified as potential therapeutic targets to counteract immunosuppression in sepsis." (PMID 38690455, 2024). "It has been reported that excessive IL-15 stimulation leads to pathological inflammatory responses similar to sepsis, resulting in the death of mice due to massive NK cell proliferation and IFN-γ production." (PMID 36776839, 2023). "It has been reported that IL-15 plays an important role in host defense in sepsis induced in mice by E. coli." (PMID 36902426, 2023). "IL-15 is an immune-adjuvant molecule that has demonstrated promise in the early stages of testing in clinically-relevant models of sepsis." (PMID 33532141, 2021). "Some of these genes, including CSFs, IFN related genes, HLA antigen genes, and IL-15 have been identified as the management targets for sepsis-induced immunosuppression." (PMID 33761636, 2021). "Recent studies imply that some novel immunomodulatory agents, including IL-7, IL-15, GM-CSF, IFN-γ, and co-inhibitory molecule blockade can reduce the clinical morbidity associated with severe sepsis and septic shock." (PMID 32197507, 2020).
Sepsis (continued). "In contrast, IL-15, which was increased or unchanged in serum of septic patients), promoted sepsis in animal models and plays an important role specifically in CD8+ T cell survival, was upregulated." (PMID 32825352, 2020). "In mouse models of sepsis, administration of IL-15 can significantly inhibit sepsis-induced apoptosis of immune competent cells through boosting Bcl-2 expression." (PMID 32197507, 2020). "Mouse NK cells exacerbate detrimental hyperinflammation in experimental sepsis, predominantly, through interleukin-15 (IL-15) induced interferon-γ production, but their dysfunction also appears to contribute to subsequent immunosuppression." (PMID 31075840, 2019). "For example, IL-15, a critical cytokine for the development of sepsis-related apoptosis, can be studied in humanized mice only after modification of the model still resulting in production of age-dependent IL-15." (PMID 30245803, 2018). "We and others have previously shown that inhibition of IL-15 protects against sepsis, as well as against both septic and aseptic arthritis development (19, –, 21)." (PMID 29440371, 2018). "At least, in diabetic rats, resistance training increasing both muscle and serum levels of IL-15 and IL-15 is one of the main protective factors in sepsis-induced muscular wasting and proteolysis in mice." (PMID 28373915, 2017). "IL-15 is also known to prevent the apoptotic depletion of innate immune cells including dendritic and NK cells during sepsis." (PMID 26859674, 2016). "Because ω-3 PUFA supplemented mice suffered increased mortality, we also examined serum IL-15, a cytokine shown to induce sepsis, as well as TNF-α." (PMID 23405155, 2013). "There was no relation between severity of organ failure and/or outcome in patients with sepsis and IL-2, IL-7, IL-15, Bim, Bax or Bcl-2 gene expression." (PMID 21711552, 2011). "Animal studies have shown that IL-15 is up-regulated in myocardial cells of sepsis mice." (PMID 41209006, 2025). "In addition, MAIT cells can respond to cytokines including IL‐12, IL‐18, IFN‐α and IL‐15,10, 15, 16, 17 all of which are elevated in the blood early in sepsis." (PMID 40041474, 2025). "Similar to our data, VEGFR2 was depressed and IL-15 elevated in a small Olink analysis of critically ill adults with sepsis (ferritin status unknown), but ANGPT1 and PDGF-subunit B levels were higher (not lower)." (PMID 39264477, 2024). "In a mouse model of sepsis, IL-15 has been shown to attenuate sepsis-induced apoptosis of natural killer (NK) cells, dendritic cells, and CD8+ T cells by increasing the expression of the anti-apoptotic protein Bcl-2, and decreasing the expression of pro-apoptotic proteins Bim and PUMA." (PMID 39720718, 2024). "In addition, IL-15 has been investigated for its role in indicating cancer-induced cachexia and its potential to prevent sepsis-induced muscle wasting." (PMID 38755201, 2024). "Immunoadjuvant therapy using IL-7 and IL-15, administration of interferon γ, and targeting PD-1, particularly to septic patients who exhibit immunosuppressive tendencies, signifies a significant forthcoming breakthrough in the realm of sepsis." (PMID 38510969, 2024). "Given that IL-15 has shown toxicity in a previous animal study, it is important to determine the optimal dosage when employing it as an immunotherapeutic agent in sepsis." (PMID 39720718, 2024). "Additionally, potential alternative strategies such as immunostimulants like IL-15 and IL-7 are proposed to counteract the immunosuppressive state induced by sepsis, although further clinical trials are warranted to validate these approaches." (PMID 38690455, 2024). "Although IL-15 has a stimulatory effect on many immune cells, it may also promote systemic inflammation and organ damage in treating sepsis and has also been shown to have potentially toxic effects." (PMID 38114466, 2023).
Sepsis (continued). "In addition to their cytolytic capacity, NK cells conventionally produce IFN-γ, but can produce IL-10 in response to IL-15 during sepsis." (PMID 35878936, 2022). "IL-15 is a pluripotent cytokine that is essential for NK cell development, survival, and function, whose stimulation has been shown to increase NK cell cytotoxicity and improve survival in sepsis." (PMID 33532141, 2021). "FMS-like tyrosine kinase 3 ligand (FLT3L) is a DC growth factor that may have the potential to ameliorate sepsis-induced immunosuppression, while IL-15 may exert potent immune-stimulatory and proliferative effects against DCs." (PMID 33532141, 2021). "Compared with wild type, IL15 knockout mice had significantly improved survival in CLP‐induced sepsis, along with reduced NK and CD8+ cells and mitigated sepsis‐induced hypothermia and organ injuries, and the severity of sepsis was restored by exogenous infusion of IL15 owing to activating NK cells." (PMID 34925807, 2021). "Therefore, IL-15 can be used in combination with other immunotherapeutic agents for sepsis treatment, such as antibodies that block PD-1 or CTLA-4, which have been found to diminish IL-10 production and PD-1 expression on CD8+ T cell." (PMID 32197507, 2020). "These properties make IL-15 an attractive candidate for immunotherapy in sepsis." (PMID 32197507, 2020). "IL-15 has anti-apoptotic properties that may prevent sepsis-induced apoptosis of immune cells in septic patients." (PMID 32407417, 2020). "IL-15 blocks sepsis-induced apoptosis in NK cells, dendritic cells, and CD8 T cells." (PMID 32731491, 2020). "Sepsis induced gut epithelial apoptosis also decreases on account of IL-15." (PMID 32731491, 2020). "An important feature of immunosuppression is T cell exhaustion, which was recently recognized following many trials for sepsis involving immunoregulatory therapies, such as PD-1 blockade, interleukin 7 administration, interleukin 15 administration, IFN-γ administration, and CTLA-4 blockade." (PMID 31440257, 2019). "Indeed, in the case of sepsis, IL-15 inhibition is beneficial in both polymicrobial and endotoxin-induced sepsis, although in the case of Gram-positive S. aureus-induced sepsis, IL-15 knockout mice have survival rates similar to those of wild-type mice." (PMID 29440371, 2018). "IL-15 is known to enhance immunogenicity through promoting the activation of dendritic cells and is upregulated in leukocytes during sepsis; therefore, targeting IL-15 within IEC may be a novel therapeutic option in patients with IBD." (PMID 29164271, 2018). "The administration of exogenous cytokines can have a marked effect on the number and function of various immune cell populations in sepsis survivors, as demonstrated by the preclinical and clinical data touting the benefits of IL-2, IL-7, IL-15, and Flt3L (among others)." (PMID 30379932, 2018). "Several such immune modulators are being advocated as potential treatments for sepsis, including cytokines (interleukin 7, interleukin 15, GM-CSF, interferon γ) and co-inhibitory molecular blockade (eg, anti-programmed cell death receptor-1 and anti-B and T lymphocyte attenuator)." (PMID 26917434, 2016). "Thus, we examined the effect of burn and sepsis on adaptive immune cell populations and the effect of IL-15 SA treatment on the host response to infection." (PMID 26859674, 2016). "Whether such IL-15 quantities are still insufficient and whether treatment with exogenous IL-15 may help correct immunological incompetence in sepsis warrant further investigation." (PMID 26322041, 2015). "IL-15 is also a pleiotropic cytokine having promising results in experimental models of sepsis." (PMID 25302303, 2014). "Consequently, mice fed diets supplemented with ω-3 PUFA suffered from increased infection-induced mortality associated with sepsis related serum LBP, IL-15 and TNF-α." (PMID 23405155, 2013).
Sepsis (continued). "• CD69 expression is enhanced on NK cells from SIRS and sepsis patients but may still be futher increased by the addition of IL-15 plus IL18." (PMID 23098236, 2012). "IL-2 gene expression was lower in bacteraemia patients compared with controls, and lower still in patients with sepsis; IL-7 gene expression was similar in control and bacteraemic patients, but lower in patients with sepsis; IL-15 gene expression was similar in the three groups." (PMID 21711552, 2011). "Parallel studies reveal interferon-γ (IFN-γ) restores monocyte functionality, while interleukin-15 (IL-15) exhibits unique immunostimulatory properties through natural killer cell activation and dendritic cell expansion—cell populations critically depleted during sepsis pathogenesis." (PMID 41256846, 2025). "Therefore, IL-15 needs further study as an immunotherapeutic agent in sepsis." (PMID 38114466, 2023). "However, IL-15 SA treatment failed to prevent burn wound sepsis-induced loss of CD4+, CD8+, B, NK and NKT cells and failed to improve bacterial clearance and survival." (PMID 26859674, 2016). "However, we recently showed in a mouse model that purified NK cells are responsive to TLR agonists in the presence of IL-15/IL-18 and that they become tolerant to this ex vivo challenge following polymicrobial sepsis, which is in favor of a deactivation of NK cells themselves." (PMID 23098236, 2012). "Plasma interleukin-10 (IL-10) (0.0 pg/ml; IQR, 0.0-4.8 vs 28.8 pg/ml; IQR, 7.5-51.7; P = 0.003) and IL-15 (0.0 pg/ml; IQR, 0.0-0.0 vs 0.0 pg/ml; IQR, 0.0-5.6; P = 0.024) levels were significantly higher in the sepsis group." (PMID 41996420, 2026). "Plasma levels of IL‐12, IL‐15, TNF, IFNγ and CXCL10 correlated with the magnitude of MAIT cell activation in sepsis patients." (PMID 40041474, 2025). "Correlation analyses of MAIT cell activation markers and soluble factors in sepsis patients revealed positive, albeit weak, correlations between the MAIT cell CD69 expression and the levels of IL‐12 and IL‐15 and with IFNγ and TNF in the plasma." (PMID 40041474, 2025). "Accumulating evidence demonstrates that blockade of inflammatory cascades effectively mitigates sepsis-induced cardiomyocyte pyroptosis, including inhibition of TNF, IL-1, IL-6, IL-7, IL-15, coagulation factors, and complement C5a." (PMID 41256846, 2025). "The MAIT cell‐activating cytokines IL‐12, IL‐15 and IL‐18, as well as TNF, IFNγ and IL‐17A, cytokines known to be produced by MAIT cells, were elevated in the plasma of sepsis patients as well as non‐sepsis patients, compared with non‐infected controls." (PMID 40041474, 2025). "The deregulation of DEGs including AKT1 (down), IFN-inducible protein 6 (IFI6, down), IL-15 (up), and ANXA1 (up) was verified in the neutrophils from patients with sepsis-induced immunosuppression as compared with controls." (PMID 33761636, 2021). "The following contents of this review will highlight the immunomodulators that improve T cell immune responses during sepsis, such as IL-7, PD1/ PDL1-specific antibodies, IFN γ, G-CSF /GM-CSF, IL-15, IL-1ra, and anti-IL-6 antibody." (PMID 32197507, 2020). "Comparison of molecules between the control and sepsis groups revealed statistically significant differences, except for IFN-α, IL-1RA, IL-1β, IL-2, IL-6, IL-7, IL-15, LIF, GM-CSF, TNF-α, CCL4, CCL5, and CXCL12." (PMID 31583025, 2019). "IL8, IL15 and HMGB1 were significantly up regulated in other sepsis cases compared to healthy controls." (PMID 28628607, 2017). "A previous study showed that IL-15 SA treatment can reverse lymphocyte dysfunction and improve survival in the cecal ligation and puncture (CLP) murine model of sepsis and in a model of Pseudomonas pneumonia." (PMID 26859674, 2016). "Treatment with IL-15 SA has been shown to prevent T cell apoptosis, ameliorate innate and adaptive immune system dysfunction and reduce mortality in the CLP model of sepsis." (PMID 26859674, 2016).
Sepsis (continued). "PC2iNTS is characterized by a cytokine profile typically described in patients with sepsis, with concomitantly raised proinflammatory (IL-6, IL-8, CXCL10, and IL-15) and anti-inflammatory (IL-10 and IL-1Ra) cytokines." (PMID 27170644, 2016). "We further assessed the impact of IL-15 SA treatment on expansion of T, NK and NKT cells and its ability to protect against Pseudomonas aeruginosa-induced sepsis in a mouse model of cutaneous burn injury." (PMID 26859674, 2016). "Results showed that IL-15 administration significantly inhibited the apoptosis of splenic CD4, CD8, NK, and DCs induced by sepsis." (PMID 25821827, 2015). "The reported benefit of treatments aimed at preventing early lymphocyte apoptosis in animal models of sepsis, such as the early supplementation with the pro-survival cytokines IL7 or IL15 is consistent with this notion." (PMID 25541945, 2014). "For what we believe is the first time, however, we also demonstrate that levels of eotaxin, IL-5, IL-15, M-CSF, MIG, MIP-1α, MIP-1β, and MIP-2 rise significantly during sepsis." (PMID 24725742, 2014). "The fish oil supplemented diet resulted in increased mortality during infection due to sepsis evident by the presence of serum LPS binding protein (LBP), IL-15 and TNF-α." (PMID 23405155, 2013). "Additionally, IL-15 enhances IFN-γ production and improves survival in the cecal ligation and puncture (CLP) sepsis model." (PMID 39720718, 2024). "Similar to adult sepsis studies, we did not observe a difference in IL-15 between preterm infants with and without sepsis." (PMID 32407417, 2020). "For the proinflammatory cytokines, the levels of IL-1β, IL-2, IL-6, and TNF-α were elevated in the early sepsis phase (2 h), but most other proinflammatory cytokines, including IL-12, IL-15, IL-17, and IFN-γ, showed significant elevation in the late sepsis phase (24–48 h)." (PMID 31354717, 2019). "Unlike IL-7, IL-15 is a potent promoter of NK cell and DC functions, which can be defective in sepsis." (PMID 26322041, 2015). "IL-15, M-CSF, MIG, MIP-1α, MIP-1β and MIP-2 promote cellular differentiation, activity, survival, recruitment and chemotaxis, confirming the complexity of the dysregulated immune response during sepsis." (PMID 24725742, 2014). "IL-15 induces sepsis as determined with IL-15 knockout mice which avoid sepsis through the lack of protease activation." (PMID 23405155, 2013). "More specifically, IL-7, IL-15, granulocyte-macrophage colony stimulating factor (GM-CSF), anti-programmed cell death receptor-1 (PD-1), and anti- B- and T-lymphocyte attenuator (BTLA) targeted the immunosuppressive status of critically patients with sepsis shock." (PMID 36439140, 2022). "Furthermore, in other mouse models of aseptic arthritis, as well as in Gram-negative and endotoxin-induced murine sepsis, inhibition of IL-15 has been beneficial with respect to both arthritis development and survival during sepsis." (PMID 29440371, 2018). "In Il-15−/− mice, the absence of IL-15 in MC increases chymase activities, leading to greater MC bactericidal responses, increased processing, and activation of neutrophil-recruiting chemokines, and improved sepsis survival." (PMID 22876248, 2012). "A recent Olink study also found that EGF levels were lower and IL-15 levels higher in children with more severe Multiple Organ Dysfunction (MOD), whether due to sepsis or not." (PMID 39264477, 2024).